MIR526A1 (microRNA 526a-1)
Synonyms: hsa-mir-526a-1; MIRN526A-1; MIRN526A1
Gene: MicroRNA gene on chromosome 19 (53,706,252 to 53,706,336, forward strand). Ensembl gene ENSG00000207629.
Gene Ontology:
Biological process: miRNA-mediated post-transcriptional gene silencing
Homologues: Orthologues: chimpanzee ptr-mir-526a-1 (100% identical). Paralogues in human: MIR518F (91% identical), MIR516B1 (89% identical), MIR516A1 (88% identical), MIR518E (88% identical), MIR519C (88% identical), MIR520C (88% identical), MIR523 (88% identical), MIR516A2 (87% identical), MIR519A2 (86% identical), MIR522 (86% identical), MIR518C (85% identical), MIR518D (85% identical), and 12 more.